AIMP1 (aminoacyl tRNA synthetase complex interacting multifunctional protein 1)
Description:
Non-catalytic component of the multisynthase complex. Stimulates the catalytic activity of cytoplasmic arginyl-tRNA synthase. Binds tRNA. Possesses inflammatory cytokine activity. Negatively regulates TGF-beta signaling through stabilization of SMURF2 by binding to SMURF2 and inhibiting its SMAD7-mediated degradation (By similarity). Involved in glucose homeostasis through induction of glucagon secretion at low glucose levels (By similarity). Promotes dermal fibroblast proliferation and wound repair. Regulates KDELR1-mediated retention of HSP90B1/gp96 in the endoplasmic reticulum (By similarity). Plays a role in angiogenesis by inducing endothelial cell migration at low concentrations and endothelial cell apoptosis at high concentrations. Induces maturation of dendritic cells and monocyte cell adhesion. Modulates endothelial cell responses by degrading HIF-1A through interaction with PSMA7.
Synonyms: EMAP-2; EMAP2; SCYE1; EMAPII; p43; HLD3
Tractability: Antibody: UniProt places it where antibodies can reach, with high confidence; its Gene Ontology location is reachable by antibodies, with medium confidence. PROTAC: UniProt records ubiquitination sites on it; ubiquitination databases record sites on it; its protein half-life has been measured.
Gene: Protein-coding gene on chromosome 4 (106,315,544 to 106,349,456, forward strand). Ensembl gene ENSG00000164022.
Subcellular location: Nucleus; Cytoplasm, cytosol; Secreted; Endoplasmic reticulum; Golgi apparatus
Subcellular location (Human Protein Atlas): Cytosol; Predicted to be secreted
Pathways (Reactome):
Developmental Biology: Transcriptional and post-translational regulation of MITF-M expression and activity
Metabolism: Selenoamino acid metabolism
Metabolism of proteins: Cytosolic tRNA aminoacylation
Gene Ontology:
Molecular function: GTPase binding; protein binding; protein homodimerization activity; tRNA binding; cytokine activity
Biological process: cell-cell signaling; leukocyte migration; negative regulation of endothelial cell proliferation; positive regulation of glucagon secretion; tRNA aminoacylation for protein translation; blood vessel morphogenesis; defense response to virus; signal transduction
Cellular component: aminoacyl-tRNA synthetase multienzyme complex; cell surface; cytosol; extracellular region; membrane; nucleus; cytoplasm; endoplasmic reticulum; Golgi apparatus
Genetic constraint (gnomAD): Loss-of-function variants: 20 observed, 31.22 expected, observed/expected ratio (o/e) 0.64, 90% interval 0.45 to 0.93. The upper end of that interval is the gene's LOEUF score, 0.93, which puts it in group 3 of 6, group 1 being the genes least tolerant of losing a copy. Missense variants: 359 observed, 373.54 expected, observed/expected ratio (o/e) 0.96, 90% interval 0.88 to 1.05. Synonymous variants: 120 observed, 127.11 expected, observed/expected ratio (o/e) 0.94, 90% interval 0.81 to 1.1.
Gene-disease validity (ClinGen):
ClinGen rates the evidence that AIMP1 causes each of these diseases.
hypomyelinating leukodystrophy 3 (autosomal recessive): Definitive. Any leukodystrophy in which the cause of the disease is a mutation in the AIMP1 gene.
Homologues: Orthologues: chimpanzee AIMP1 (99% identical), macaque AIMP1 (96% identical), rabbit AIMP1 (91% identical), dog AIMP1 (91% identical), pig AIMP1 (90% identical), rat Aimp1 (86% identical), guinea pig AIMP1 (84% identical), mouse Aimp1 (83% identical), tropical clawed frog aimp1 (71% identical), zebrafish aimp1a (65% identical), Drosophila melanogaster AIMP1 (45% identical), zebrafish aimp1b (42% identical).
Diseases named in the same sentence as AIMP1 in open-access papers:
AIMP1 is named in the same sentence as 67 diseases in open-access papers, as found by Europe PMC text mining. Sharing a sentence is not in itself a finding about the gene and the disease. The quoted sentences say what the papers report.
glioma (15 papers, 2015 to 2025). A benign or malignant brain and spinal cord tumor that arises from glial cells (astrocytes, oligodendrocytes, ependymal cells). "There was a trend for increased AIMP1 expression in recurrent gliomas compared with primary gliomas (P = 0.058)." (PMID 40874786, 2025). "For example, discovering the role of single gene in a single tumor, they argued in detail the identity of SCN3B and CDK2 in glioma, and proved the role of AIMP1, CNIH4 in head and neck squamous cell carcinoma." (PMID 40108724, 2025). "Studies such as those on SCN3B in glioma, CDK2 in glioma, AIMP1 in head-neck squamous cell carcinoma and CNIH4 in head and neck squamous cell carcinoma demonstrate the diverse applications of TCGA data in cancer research." (PMID 40290723, 2025). "Recently, analysis of 297 glioma samples from the Chinese Glioma Genome Atlas for local immune signature genes identified AIMP1, FOXO3, and ZBTB16 as positive prognostic indicators well correlated with patient overall survival (OS)." (PMID 29379495, 2017). "Thus, although the focus of this study is antiangiogenesis therapy, it should be noted that AIMP1/2/3 inhibition may be a potential therapeutic approach that may benefit gliomas." (PMID 40874786, 2025). "AIMP1-cg24015814 and AIMP3-cg20512532 were also associated with improved DFS with bevacizumab treatment in astrocytoma at multivariate analysis and may thus be of particular importance in gliomas in general, warranting further investigations which is beyond the scope of this study." (PMID 40874786, 2025). "While TCGA has revolutionized cancer biomarker discovery, exemplified by studies identifying SCN3B in glioma, CDK2 in glioma prognosis, AIMP1/CNIH4 in head-neck squamous carcinoma, and RAD50 in breast cancer, its limitations must be acknowledged." (PMID 40860678, 2025). "Here, we report aberrant protein expressions of AIMP1, AIMP2, and AIMP3 in gliomas compared with normal brain and their significantly higher mRNA expression in higher-grade compared with lower-grade tumors." (PMID 40874786, 2025).
fibrosarcoma (7 papers, 2012 to 2022). A malignant mesenchymal fibroblastic neoplasm affecting the soft tissue and bone. "Endothelial Monocyte Activating Polypeptide II (EMAP II, also known as AIMP-1, Scye-1, and p43), a single chain polypeptide protein originally isolated from a murine fibrosarcoma, is ubiquitously expressed as a 34-kDa intracellular protein." (PMID 22412987, 2012).
colorectal cancer (5 papers, 2006 to 2022). A primary or metastatic malignant neoplasm that affects the colon or rectum. "Deregulations of pathway members including AIMP1, AIMP2 and AIMP3 were observed in gastric and colorectal cancer." (PMID 35044082, 2022). "The plasma AIMP1, KARS1, and IL-10 levels were significantly higher in the colorectal cancer patients than the healthy controls (p < 0.0001)." (PMID 32075312, 2020). "The expression of AIMP1, AIMP2, and AIMP3 was downregulated in gastric and colorectal cancer, which might result in their inactivation of tumor suppressor functions and tumor development." (PMID 32709848, 2020).
glioblastoma (5 papers, 2015 to 2024). The most malignant astrocytic tumor (WHO grade IV). "Elevated expression of AIMP1 was recently shown to correlate positively with OS in glioblastoma." (PMID 29379495, 2017). "Genetic ablation of AIMp1 enhances TH2-biased airway hyperreactivity in a model of allergic airway inflammation, and upregulated AIMp1 gene expression was recently identified as part of a good-prognosis gene signature in glioblastoma multiforme." (PMID 29379495, 2017).
breast carcinoma (4 papers, 2017 to 2025). "In basal-like breast cancer, elevated levels of AIMP1 expression were found to be positively correlated with both increased numbers of activated tumor-infiltrating DCs and a TH1 T-cell signature." (PMID 29379495, 2017). "In addition, AIMP1 significantly inhibited the growth of breast cancer 4T1 cells in mice, accompanied by decreased myeloid-derived suppressor cell (MDSC) population in the spleens and tumor sites." (PMID 33330488, 2020). "In-depth studies found that AIMP1 inhibited the expansion and suppressive functions of MDSCs by reducing the activity of signal transducers and activators of transcription (STATs), AKT and ERK, indicating that AIMP1 might be a key target of breast cancer immunotherapy strategies." (PMID 33330488, 2020). "Administration of recombinant E. coli-expressed human AIMp1 protein to tumor-bearing mice has been shown to have tumor inhibitory effects in a human xenograft model of stomach cancer as well as EG7 lymphoma, breast cancer, and others." (PMID 29379495, 2017). "Strong trends toward enhanced survival among patients with high AIMP1 expression were observed in ovarian cancer, breast cancer (data not shown) and melanoma." (PMID 29379495, 2017).
systemic lupus erythematosus (4 papers, 2014 to 2025). An autoimmune multi-organ disease typically associated with vasculopathy and autoantibody production. "AIMP1, as an auxiliary factor of the large macromolecular aminoacyl tRNA synthetase complex, has been implicated in diverse pathologies including AD, systemic lupus erythematosus (SLE) and cancer." (PMID 40522094, 2025). "It was also reported that AIMP1/p43 inhibited Lupus-like autoimmune disease by decreasing cell surface expression of gp96." (PMID 24816397, 2014). "AIMP1/p43 knockout mice show lupus-like autoimmune disease phenotype." (PMID 24816397, 2014). "Patients with systemic lupus erythematosus (SLE) have significantly higher levels of serum AIMP1 than healthy control." (PMID 36159396, 2022). "We previously demonstrated the clinical potential of AIMP1 as a biomarker in patients with rheumatoid arthritis and systemic lupus erythematosus (SLE)." (PMID 31236412, 2019).
viral infection (4 papers, 2017 to 2022). "Upon infection of the H1N1 influenza A virus, AIMP1 is upregulated in bronchial epithelial cells, exhibiting a possible role for AIMP1 in response to viral infection." (PMID 35337020, 2022). "AIMP1 is also upregulated in bronchial epithelial cells after influenza A infection, exhibiting a possible role for AIMP1 in response to viral infection." (PMID 35153822, 2021). "We have demonstrated the importance of AIMp1 in TH1 polarization during antitumor immunity both in vivo and in vitro; however, the microarray data indicated that AIMp1 function might also be highly relevant to immunity against intracellular virus infection." (PMID 29379495, 2017).
autoimmune disease (3 papers, 2014 to 2020). A disorder resulting from loss of function or tissue destruction of an organ or multiple organs, arising from humoral or cellular immune responses of the individual to their own tissue constituents. "Using the finding that HCV E2 interacted with AIMP1/p43, we presented evidences and possible mechanisms how HCV E2 caused liver fibrosis and autoimmune disease via interaction with AIMP1/p43 in this study." (PMID 24816397, 2014). "Thus, the underlying autoimmune disease should be considered when determining cut-offs of serum AIMP1 to define high disease activity." (PMID 31236412, 2019). "Although we did not include patients with SLE in the present study, and thus could not directly compare serum AIMP1 between the two diseases, these results suggest that the dynamic range of the serum concentration of AIMP1 to estimate disease severity might be autoimmune disease-specific." (PMID 31236412, 2019). "Thus, AIMP1 may participate in the pathogenesis of autoimmune diseases, especially AAV." (PMID 31236412, 2019). "Notably, a neutralizing antibody MHM6 inhibited the secretion of TNF-α induced by AIMP1 via competing with IgE for binding to CD23, suggesting that the interaction between AIMP1 and CD23 in monocytes might play an important role in autoimmune diseases." (PMID 32709848, 2020).
head and neck squamous cell carcinoma (3 papers, 2023 to 2025). A squamous cell carcinoma that arises from any of the following anatomic sites: lip and oral cavity, nasal cavity, paranasal sinuses, pharynx, larynx, and salivary glands. "Targeting six immune-related genes (CXCL5, ADM, FGF9, AIMP1, STC1, and CDKN2A) in individuals diagnosed with head and neck squamous cell carcinoma has shown promising results in immunotherapy triggered by periodontal disease." (PMID 37675228, 2023).
hypomyelinating leukodystrophy (3 papers, 2019 to 2024). "In addition, variants in two non-aaRS MSC constituents, i.e., AIMP1 and AIMP2, also cause leukodystrophy, although this is likely to be secondary to a primary neurodegenerative process." (PMID 38769304, 2024).
melanoma (3 papers, 2017 to 2020). A malignant, usually aggressive tumor composed of atypical, neoplastic melanocytes. "In this experiment melanoma tumor growth in recipient mice vaccinated with WT unloaded BMDCs (mock-electroporated) was nearly identical to that of mice vaccinated with AIMp1−/− antigen-loaded BMDC." (PMID 29379495, 2017). "BMDC-expressed AIMp1 is critical for the clearance of immunogenic B16-OVA melanoma tumor by SIINFEKL + OVA-loaded BMDC vaccination in vivo; whereas the presence of AIMp1 in the germline of recipient mice appeared to have almost no impact upon tumor regression nor survival." (PMID 29379495, 2017). "Previous literature has suggested a potential role for AIMp1 in TH1 immunity, and our work demonstrated BMDC-expressed AIMp1 is required for vaccine-mediated melanoma tumor rejection." (PMID 29379495, 2017). "To determine if intrinsic AIMp1 might possess inherent antitumor properties under conditions of physiologic homeostasis, we inoculated AIMp1−/− mice with B16F10 melanoma and observed a tumor growth rate nearly double that exhibited in WT animals." (PMID 29379495, 2017). "Even further, the ability to inhibit B16-OVA melanoma tumor growth through vaccination depended solely upon the AIMp1 phenotype of the BMDC vaccine but not upon any other host immune cell in the recipient mouse." (PMID 29379495, 2017). "The importance of AIMp1 to TH1 antiviral and antitumor immunity was also demonstrated by in vivo model systems of melanoma and influenza virus infection as well as analysis of the nearly 9,000 primary human tumors in The Cancer Genome Atlas (TCGA) database to which outcomes data could be linked." (PMID 29379495, 2017).
Alzheimer disease (2 papers, 2022 to 2025). A progressive, neurodegenerative disease characterized by loss of function and death of nerve cells in several areas of the brain leading to loss of cognitive function such as memory and language. "Studies have also shown that AIMP1 participated in pathological progression such as Alzheimer ‘s disease (AD) and cancer." (PMID 40522094, 2025).
osteoarthritis (2 papers, 2016 to 2024). A noninflammatory degenerative joint disease occurring chiefly in older persons, characterized by degeneration of the articular cartilage, hypertrophy of bone at the margins and changes in the synovial membrane. "Further, AIMp1-mediated inhibition of TGF-β signaling in chondrocytes propagates osteoarthritis pathogenesis." (PMID 38975338, 2024). "Furthermore, we assessed the role of AIMP1 in degenerated chondrocytes isolated from osteoarthritis (OA) patient." (PMID 26890138, 2016). "In addition, we observed that the AIMP1 expression level was significantly increased in osteoarthritis (OA) patient-derived degenerated chondrocytes compared with healthy control." (PMID 26890138, 2016).
alopecia (1 paper, 2024). Hair loss usually from the scalp. "Further studies that confirm AIMP1 secretion and its regulatory function on DPCs in alopecia can establish AIMP1 as a promising therapeutic target for hair loss treatment." (PMID 39494335, 2024). "Future research aimed at identifying the transcriptional regulators of AIMP1 and elucidating its aging-associated regulatory mechanisms, along with the discovery of compounds capable of reversing this decline, will facilitate the development of promising therapeutics for hair loss." (PMID 39494335, 2024). "Moreover, AIMP1 presents a potential therapeutic target for age-related hair loss." (PMID 39494335, 2024). "Our findings indicate that AIMP1 regulates hair growth through its interaction with DPCs and suggests that AIMP1, a component of the multi-tRNA synthetase complex, and its active domain, TN41, are potential therapeutic candidates for the treatment of hair loss." (PMID 39494335, 2024).
influenza (1 paper, 2017). An acute viral infection of the respiratory tract, occurring in isolated cases, in epidemics, or in pandemics; it is caused by serologically different strains of viruses (influenzaviruses) designated A, B, and C, has a 3-day incubation period, and usually lasts for 3 to 10 days. "The data suggested that AIMp1 also impacts B-cell or Tfh cell function with regard to Ig isotype of antibodies critical for influenza virus protection." (PMID 29379495, 2017).
Intellectual disability (1 paper, 2021). "Homozygous pathogenic variants in AIMP1 have been reported to cause moderate to severe intellectual disability suggesting that imbalances in EMAP-II-like functions are sufficient to cause developmental disorders." (PMID 34536092, 2021).
lung adenocarcinoma (1 paper, 2016). A carcinoma that arises from the lung and is characterized by the presence of malignant glandular epithelial cells. "Mouse embryonic fibroblast (MEF) of AIMP1-knockout mice reportedly exhibit increased phosphorylation of Smad2 and Smad3, and knockdown of AIMP1 using short-interfering RNA (siRNA) promotes phosphorylation of Smad2 in human lung adenocarcinoma A549 cells." (PMID 26890138, 2016).
lupus nephritis (1 paper, 2024). Glomerulonephritis in the context of systemic lupus erythematosus. "When AIMp1 is dysregulated, gp96 is targeted to the cell membrane surface where it triggers Th1 immune responses including the auto-antibodies involved in the pathogenesis of systemic lupus erythromatosus and lupus nephritis." (PMID 38975338, 2024).
periodontal disease (1 paper, 2023). "Furthermore, CXCL5, ADM, FGF9, AIMP1, STC1, and CDKN2A might have a significant impact on the development of HNSC caused by periodontal disease." (PMID 37675228, 2023).
vasculitis (1 paper, 2019). "We investigated whether serum aminoacyl-tRNA synthetase-interacting multifunctional protein-1 (AIMP1) could predict severe cases of antineutrophil cytoplasmic antibody (ANCA)-associated vasculitis (AAV) based on the Birmingham vasculitis activity score (BVAS)." (PMID 31236412, 2019). "Hence, in this study, we investigated whether serum AIMP1 could be used to estimate the cross-sectional severity of AAV patients based on the Birmingham vasculitis activity score (BVAS) in a prospective cohort of AAV patients." (PMID 31236412, 2019).